POU3F2 (POU class 3 homeobox 2)
Diseases named in the same sentence as POU3F2 in open-access papers (continued):
Sharing a sentence is not in itself a finding about the gene and the disease.
glioblastoma (continued). "To validate the data from bulk mRNA seq, we selected a set of neural and glial‐specific genes (i.e., PAX6, BRN2/POU3F2, NF‐L/NEFL, and GFAP) showing high expression in the GLICO model in comparison to independently cultured glioblastoma spheroids or standard glioblastoma 2D culture." (PMID 36744875, 2023). "In glioblastomas, cycle-dependent kinase 5 (CDK5) phosphorylates DRP1 at Ser616 and increases mitochondrial cleavage, which then induces the expression of stemness genes (OLIG2, OCT4, NANOG, NESTIN, POU3F2, CD133, SSEA1)." (PMID 37370081, 2023). "It is also in combination with POU3F2, SALL2, and OLIG2, able to induce glioblastoma tumor growth." (PMID 34021259, 2021). "In cancer stem cells, by the induction of a core set of neurodevelopmental transcription factors (POU3F2, SOX2, SALL2, and OLIG2) that are essential for glioblastoma propagation, differentiated glioblastoma cells can be fully reprogrammed into induced stem-like tumor-propagating cells." (PMID 31375149, 2019). "To ascertain the functional relevance of this association, we focused on three transcription factors members of this stem signature SOX9, POU3F2 and OLIG2, since the knockdown of these factors has previously been reported to inhibit glioblastoma cell tumorigenicity in vivo." (PMID 29149419, 2018). "The inhibition of switch genes highly correlates with the activation of genes related to neural development and differentiation, such as the 4-core OLIG2, POU3F2, SALL2, SOX2, whose induction has been shown to be sufficient to reprogram differentiated glioblastoma into stem-like cells." (PMID 30497369, 2018). "In glioblastoma, SALL2, together with SOX2, POU3F2, and OLIGO2, reprogrammed differentiated tumor cells into tumor stem cells, and also, SALL2 was one of the partners of SOX2, suggesting SALL2 may be essential for the homeostasis of NSCs in the nervous system in vivo as well." (PMID 39349437, 2024). "The transcription factor BRN2, also known as POU3F2 and N-OCT3, plays a critical role in neurogenesis and drives proliferation in a range of cancer types with neural or neuroendocrine origins, including glioblastoma, neuroblastoma, small cell lung cancer, and neuroendocrine prostate cancer." (PMID 34140478, 2021).
glioma (18 papers, 2012 to 2025). A benign or malignant brain and spinal cord tumor that arises from glial cells (astrocytes, oligodendrocytes, ependymal cells). "METTL3 is also upregulated in glioblastoma, and silence of METTL3 inhibits the growth of glioma stem cells by downregulating POU3F2, SOX2, SALL2, OLIG2, and other glioma recombinant factors." (PMID 35571490, 2022). "More importantly, Olig2 protein is synergistic with Sox2, Pou3f2 and Sall2 and is a key transcription factor of glioma initiating cells." (PMID 32943100, 2020). "Consistent with NS-culture-derived glioma cells with high invasiveness, genes highly expressed in 51A were those encoding markers of neural stem/precursor cells (NANOG, POU3F2, POU5F1, and SALL2), and pro-invasive proteins (AGAP2, EPHA2, FOXM1, PDGFRA, and TNC)." (PMID 29113349, 2017). "METTL3 silencing reduced the expression of the glioma reprogramming factors POU3F2, SOX2, SALL2 and OLIG2, and suppressed GSC proliferation in neurosphere assays derived from human glioma cell lines." (PMID 37444417, 2023). "POU3F2 decreased upon SFRP2-overexpression and correlated positively to SOX2 expression in the CCLE glioma cell lines." (PMID 34021259, 2021). "The change in m6A modification and the transcript level of four glioma reprogramming factors (SOX2, SALL2, OLIG2 and POU3F2) and selected transcripts were validated by m6A RIP-PCR and RT-qPCR." (PMID 30781903, 2019). "IMP3 silencing also resulted in the downregulation of four glioma reprogramming transcription factors- OLIG2, POU3F2, SOX2 and SALL2 in GSCs." (PMID 28465487, 2017). "Indeed, POU3F2, SOX2, SALL2, and OLIG2 have been shown to be the core set of transcription factors essential for GBM propagation, which are within the set of 19 transcription factors (including SOX1) required for successful reprogramming of differentiated glioma cells into GSCs48." (PMID 28425506, 2017).
prostate carcinoma (13 papers, 2017 to 2025). A carcinoma that arises from epithelial cells of the prostate gland. "MUC1‐C is involved in lineage plasticity for NEtD in prostate cancer, with its expression correlating with POU3F2 (BRN2) and the NEPC score, of which BRN2 has been identified as NE master TF in NEtD." (PMID 39372390, 2024).
schizophrenia (12 papers, 2011 to 2024). A major psychotic disorder characterized by abnormalities in the perception or expression of reality. "POU3F2 encodes a transcription factor which mainly expresses in the central nervous system and has known key regulatory roles in schizophrenia and bipolar disorder." (PMID 33539344, 2021). "Therefore, we speculated that POU3F2 potentially represents one of the common genetic bases underlying schizophrenia and METH use." (PMID 33823794, 2021). "From a mechanistic point of view, it was shown that the transcription factor POU3F2 is involved, since TRIM8 expression levels were induced upon POU3F2 binding to a schizophrenia-associated SNP, located within the TRIM8 promoter area." (PMID 36139694, 2022). "POU3F2 and PAX6 were found to regulate the transcription of TRIM8 as well as the VRK2, other genes associated with schizophrenia and bipolar disorder." (PMID 35546872, 2022). "When POU3F2 is overexpressed in NSCs, several genes which are differentially expressed in the prefrontal cortex of people suffering from schizophrenia and bipolar disorder, are dysregulated." (PMID 35546872, 2022). "Moreover, POU3F2 is involved in schizophrenia, the syndrome and pathology of which are very similar to METH addiction." (PMID 33823794, 2021). "Interestingly, two other POU domain transcription factors, Pou3f2 and Pou3f3 are suspected to be involved in schizophrenia due to their effect on cortical neuron migration." (PMID 31787878, 2019).
Intellectual disability (6 papers, 2014 to 2021). "Deletions resulting in loss of one copy of POU3F2 cause a disorder of variable developmental delay, intellectual disability, and susceptibility to obesity." (PMID 33539344, 2021). "This is consistent with our recent finding that genes regulated by TF POU3F2 showed a 2.7-fold enrichment for loss-of-function de novo mutations in ASD probands which are known to cause comorbid intellectual disability." (PMID 34493297, 2021). "POU3F2 has been linked to developmental and language delays, intellectual disability, schizophrenia and autism spectrum disorders." (PMID 25431551, 2014). "POU3F2 codes for a member of the POU family of transcription factors, and has been implicated in SZ, and more recently in BD, developmental delay, and intellectual disability." (PMID 28321286, 2017). "POU3F2 also interacts with PQBP1, a protein involved in neurite growth and neuron projection, and linked to intellectual disability." (PMID 25431551, 2014). "POU3F2 is also expressed at the level of the corpus callosum, and it interacts with PQBP1, in turn linked to developmental delay and microcephaly and to intellectual disability." (PMID 26136701, 2015).
Obesity (6 papers, 2016 to 2025). Accumulation of substantial excess body fat. "Mutations in zebrafish lepr, mcr4, and pou3f2 have been generated, although few obesity-related studies have been performed as of yet." (PMID 27857842, 2016). "Notably, obesity and hyperphagia—likely due to hypothalamic dysfunction—are disproportionately observed in individuals carrying POU3F2 mutations." (PMID 40498903, 2025). "For example, mutations in SIM1, leptin receptor (LEPR), pro-opiomelanocortin (POMC), melanocortin 4 receptor (MC4R), and more recently, POU3F2 have all been associated with severe obesity, suggesting a convergence on the leptin-melanocortin pathway in association with oxytocin." (PMID 27857842, 2016). "Our findings implicate many genes previously associated with obesity (e.g. PTBP2, TMEM18, MYT1L, POU3F2, SIM1, SH2B1), and also identified other potentially relevant candidates including TAS1R3, ALOX5AP, and GAS6." (PMID 29441128, 2018). "Small 6q16.1 deletions encompassing the POU3F2 gene were identified in 10 individuals presenting with obesity, hyperphagia and IDDs." (PMID 29441128, 2018).
small cell lung carcinoma (6 papers, 2006 to 2023). Small cell lung cancer (SCLC) is a highly aggressive malignant neoplasm, accounting for 10-15% of lung cancer cases, characterized byrapid growth, and early metastasis. "In small cell lung cancer lines, both gain-of-function and loss-of-function strategies have shown that POU3F2 regulates the expression of achaete-scute homolog-like 1 (ASCL1), which functions as a growth enhancer and helps tumor cells escape anti-cancer immune responses." (PMID 27271588, 2016).
autism (4 papers, 2018 to 2025). Persistent deficits in social interaction and communication and interaction as well as a markedly restricted repertoire of activity and interest as well as repetitive patterns of behavior. "We pinpoint a novel autism gene POU3F2, which encodes a key transcription factor regulating multiple autism risk genes implicated in exome sequencing studies." (PMID 33539344, 2021). "Together, these studies define POU3F2 as an activator of canonical Wnt signalling and mechanistically link two high-confidence autism genes, ADNP and POU3F2, in the regulation of neurodevelopment." (PMID 40498903, 2025). "From the single gene annotation analysis, it can be seen that the abnormalities of MED13, POU3F2, and USP8 have been confirmed to induce autism." (PMID 32273901, 2020).
bipolar disorder (4 papers, 2011 to 2022). A disorder of the brain that causes unusual shifts in mood, energy, activity levels and the ability to carry out day-to-day tasks. "Genome-wide association studies revealed a risk loci for bipolar disorder downstream of POU3F2, and a region around KLHL32, GPR63 and NDUFA4 associated with Tourette syndrome and obsessive-compulsive disorder, indicating the importance of these enriched regions for establishing cortical functions." (PMID 26076492, 2015).
breast carcinoma (4 papers, 2019 to 2022). "According to the result of TF analysis, although most of the TFs have been reported to be associated with breast cancer, there were still TFs such as EOMES, POU3F2, NR3C1, and RUNX1 that were less reported in breast cancer." (PMID 36313438, 2022). "We used a bioinformatic approach [cBioPortal;] to determine if BRN2/POU3F2 gene expression correlates with breast cancer patient survival and compare BRN2 gene expression between hormone receptor-positive and basal-like subtypes of breast cancer." (PMID 33513758, 2021). "Our analysis of breast cancer patient data from the Breast Invasive Carcinoma dataset (TCGA, PanCancer Atlas) revealed a significant, positive correlation between high expression of the BRN2/POU3F2 gene and poor patient survival." (PMID 33513758, 2021).
lung carcinoma (4 papers, 2016 to 2025). "Moreover, given its association with Pou3f2 and Mms22l, Pelomonas might play a role in susceptibility to lung cancer and other related lung diseases." (PMID 37264412, 2023).
autism spectrum disorder (3 papers, 2011 to 2025). A spectrum of developmental disorders that includes autism, and Asperger syndrome. "Finally, we describe five individuals with autism spectrum disorder that harbour loss-of-function mutations in POU3F2, enhancing the genetic evidence for its critical role in human neurodevelopment." (PMID 40498903, 2025).
metastatic melanoma (3 papers, 2015 to 2023). A melanoma that has spread from its primary site to another anatomic site. "miR-211 is shown to repress the POU3F2/BRN2 transcription factor in normal melanocytes, and it is decreased in metastatic melanoma cells compared to normal melanocytes." (PMID 25880082, 2015).
neuroblastoma (3 papers, 2018 to 2021). Neuroblastoma (NB) is the most common solid, extracranial childhood tumor. "Indeed, POU3F2/OCT3 overexpression has been correlated with neuroblastoma and glioblastoma in both human brain and neuroblastoma-derived cell lines (SH-SY5Y)." (PMID 29725501, 2018).
brain tumor (2 papers, 2019 to 2021). "It was further supported by using lipopolymeric nanoparticle-containing combo siRNA (OLIG2, POU3F2, SALL2, and SOX2) targeting brain tumor-initiating cells (BTICs) in a mouse brain tumor model." (PMID 34944911, 2021).
colon cancer (2 papers, 2018 to 2020). "It has been observed that POU3F2 conduced to cellular responses against oxaliplatin in human colon cancer cells by regulating tNOX." (PMID 31920461, 2020).
gastric cancer (2 papers, 2016 to 2018). A primary or metastatic malignant neoplasm involving the stomach. "Here, we examined the association between POU3F2 and tNOX expression in stomach cancer cells." (PMID 27271588, 2016). "As a previous study showed that the POU domain transcription factor, POU3F2, positively regulates tNOX expression in gastric cancer cells, we examined the potential involvement of POU3F2 in this system." (PMID 30029680, 2018). "Moreover, we show that the expression levels of POU3F2 and tNOX are correlated and that changes in their levels can alter the proliferation, migration and invasion of AGS gastric cancer cells." (PMID 27271588, 2016). "The protein expression levels of POU3F2 and tNOX are positively correlated, and that overexpression of POU3F2 (and the corresponding upregulation of tNOX) enhanced the proliferation, migration and invasion in AGS (human gastric carcinoma) cells." (PMID 27271588, 2016).
Adrenal insufficiency (1 paper, 2014). Insufficient production of steroid hormones (primarily cortisol) by the adrenal glands. "It is interesting to note that human chromosome 6 deletions that affect POU3F2, a homolog of Vvl, have been associated with hypogonadotropic hypogonadism and adrenal insufficiency, making it possible that Vvl is a conserved regulator of steroid biosynthesis." (PMID 24945799, 2014).
Alagille syndrome (1 paper, 2017). "In this regard, Pou3f2 could have a role in the human vascular diseases caused by mutations in Notch family members, such as Alagille syndrome and cerebral autosomal dominant arteriopathy with subcortical infarcts and leukoencephalopathy (CADASIL)." (PMID 28323620, 2017).
Cognitive impairment (1 paper, 2021). Abnormal cognition is characterized by deficits in thinking, reasoning, or remembering. "POU3F2Δ/Δ mice in which all three homopolymeric amino acid repeats were deleted from the POU3F2 transactivation domain displayed cognitive impairments in object recognition and object location tests, suggesting that POU3F2 is involved in cognitive function." (PMID 33823794, 2021).
endometriosis (1 paper, 2025). The growth of functional endometrial tissue in anatomic sites outside the uterine body. "The role of “hubs” in these endometriosis-significant interactions was performed by proteins such as MYC (participates in 7 pair interactions), POU3F2 (6 pair interactions) and CTCF (4 pair interactions)." (PMID 41373783, 2025).
Ewing sarcoma (1 paper, 2025). A small round cell tumor that lacks morphologic, immunohistochemical, and electron microscopic evidence of neuroectodermal differentiation. "Among our 12 MTF candidates, only POU3F1 and POU3F2 were reported as dependencies in Ewing sarcoma (among 28 TFs, 291 genes, Supp." (PMID 41444391, 2025). "The three MTFs (POU3F2 & SOX6 & IKZF2) colocalised in 50% of top 100 Ewing sarcoma SEs." (PMID 41444391, 2025). "Data 5), we selected six MTFs (TCF12, SOX6, POU3F1, POU3F2, NKX2-2, and IKZF2) as putative members of the Ewing sarcoma CRC, based on fulfilling at least two out of these three criteria." (PMID 41444391, 2025).
Hypertension (1 paper, 2020). The presence of chronic increased pressure in the systemic arterial system. "Finally, the TF (HAND1, E4BP4, ESR1, VBP, ELK-1, POU3F2) associated with LV remodeling in hypertension were confirmed to act a crucial role in correlated heart diseases." (PMID 32664164, 2020).
hypopituitarism (1 paper, 2025). A condition of diminution or cessation of secretion of one or more hormones from the anterior pituitary gland. "These potentials roles are supposed in several mice studies, while hypopituitarism seemed to be due to the association of SIM1 with other variants, such as POU3F2 gene mutations." (PMID 40428410, 2025).
lung adenocarcinoma (1 paper, 2021). A carcinoma that arises from the lung and is characterized by the presence of malignant glandular epithelial cells. "(b) Heat map of the PEA3 family ETS transcription factors (ETV1, ETV4, and ETV5) and neuroendocrine transcription factors (ASCL1, NEUROD1, INSM1, and POU3F2 [BRN2]) in small cell lung cancer and lung adenocarcinoma cell lines." (PMID 34121659, 2021).
neural tumors (1 paper, 2011). "It has also recently been shown to be a criticalcomponent in the cocktail, along with Pou3f2 and Mytl1, for directly reprogrammingfibroblasts to neurons, and it has aberrant expression in neural tumors such asglioblastoma." (PMID 21483754, 2011).
sudden infant death syndrome (1 paper, 2013). Unexpected death in infancy which remains unexplained following autopsy, review of the medical history, and investigation of the death circumstances and death scene. "GeneCards documents the involvement of POU3F2 in the neurogenesis pathway and in SIDS (Sudden Infant Death Syndrome) susceptibility pathways." (PMID 24172660, 2013).